RNU7-129P (RNA, U7 small nuclear 129 pseudogene)
Gene: Small nuclear RNA gene on chromosome 18 (12,400,412 to 12,400,473, forward strand). Ensembl gene ENSG00000251937.
Homologues: Orthologues: chimpanzee U7 (98% identical), macaque U7 (95% identical). Paralogues in human: RNU7-48P (85% identical), RNU7-2P (82% identical), RNU7-55P (82% identical), U7 (82% identical), RNU7-24P (81% identical), RNU7-25P (81% identical), RNU7-26P (81% identical), RNU7-79P (81% identical), RNU7-88P (81% identical), RNU7-8P (81% identical), RNU7-11P (79% identical), RNU7-123P (79% identical), and 143 more.